FOXF1 (forkhead box F1)
Diseases named in the same sentence as FOXF1 in open-access papers (continued):
Sharing a sentence is not in itself a finding about the gene and the disease.
cancer (47 papers, 2014 to 2025). A tumor composed of atypical neoplastic, often pleomorphic cells that invade other tissues. "In the tumour microenvironment, FOXF1 also stimulates cancer-associated fibroblasts to facilitate lung cancer tumorigenesis and migration." (PMID 32372224, 2020). "Overexpression of FoxF1 promoted invasion and metastasis of breast carcinomas and enhanced the tumor-promoting properties of cancer-associated fibroblasts." (PMID 26625197, 2016). "This is also in line with various studies demonstrating cell-cycle-associated regulation of cancer; consequently, cell-cycle inhibitors like FOXF1 might be considered as a therapeutic target in the management of cancer." (PMID 32370197, 2020). "In recent years, FOXF1 proteins were implicated in cancer progression." (PMID 32370197, 2020). "The involvement of FOXF1 in tumor pathogenesis further supports the role of epigenetic mechanisms in cancer." (PMID 40869921, 2025). "Hypermethylation of the phosphodiesterase 3A (PDE3A) gene correlates with cisplatin resistance, and the epigenetic activation of forkhead box protein F1 (FOXF1) confers cancer stem cell properties to cisplatin resistance." (PMID 41008870, 2025). "Since homozygous deletion of Foxf1 in mouse endothelial cells (Pdgfb-CreERtg/+;Foxf1fl/fl) is lethal, we used heterozygous mice for cancer studies (Pdgfb-CreERtg/+;Foxf1fl/+; abbreviated as endFoxf1+/−)." (PMID 38589650, 2024). "FOXF1 belongs to the family of winged-helix transcription factors and has been reported to be involved in the development of many types of cancer." (PMID 35468741, 2022). "For example, the hypermethylation of the IGFBP3 promoter, and upregulation of forkhead box F1 (FOXF1) expression was found to trigger resistance to cisplatin and the acquisition of cancer stem cell (CSC)-like phenotypes in NSCLC cells." (PMID 36230484, 2022). "The association of FOXF1-deficiency with biliary tract malformations described in mice and its importance in various carcinomas led us to use FOXF1 antibody as a potential immunohistochemical marker of CCA and metastatic PDAC." (PMID 34257615, 2021). "Being a downstream target of the hedgehog signaling pathway, many studies suggested that FOXF1 is positively correlated with cancer development." (PMID 32370197, 2020). "Our results demonstrated significantly lowered gene expression of FOXF1 not only in cancer tissues, but also in H441 and H1299 cell lines, compared to their respective normal controls." (PMID 32370197, 2020). "Discovery of pharmacological agents that inactivate or decrease FoxF1 in tumor cells can be beneficial for treatment of cancers resistant to conventional chemotherapy." (PMID 26625197, 2016). "First, by using qRT-PCR, we detected the host gene FOXF1, which plays an important role in cancer cell invasion and migration, in FENDRR-overexpressing cells, FENDRR-knockdown cells, and control cells." (PMID 25167886, 2014).
cancer (continued). "Additionally, epigenetic activation of FOXF1 confers cancer stem cell properties promotes cisplatin resistance in NSCLC." (PMID 39458997, 2024). "H19 and FOXF1 adjacent non-coding developmental regulatory RNA (FENDRR) are oncogenic lncRNAs that are associated with cancer invasion, proliferation, and migration in various types of cancers." (PMID 38414063, 2024). "However, hypomethylation of FOXF1 facilitates cell proliferation, acquires cancer stem properties, and inhibited cell apoptosis to induce cisplatin resistance in NSCLC." (PMID 35860691, 2022). "Additionally, the Forkhead box (FOX) family of transcription factors (FOXF1, FOXS1, FOXM1, FOXK1, FOXP4, and FOXC1) play a role in cell differentiation and proliferation and are implicated in cancer and drug resistance." (PMID 35854219, 2022). "Also, circNASP promoted key OS phenotypes by targeting miR-1253/FOXF1 signaling and circTADA2A promoted cancer phenotypes in OS by sponging miR-203a-3p and modulating CREB3." (PMID 34716285, 2021). "According to our results, the in silico analysis of FENDRR and FOXF1 expression from Cancer Cell Line Encyclopedia (CCLE) database showed a significant positive correlation between FENDRR and FOXF1 in 1036 cancer cell lines (p<0.001), and in particular 116 NSCLC cancer cell lines (p<0.00001)." (PMID 32284793, 2020). "In biology research, FOXF1 has been recently identified as important cancer-related gene." (PMID 30598067, 2018). "Interestingly, FOXF1 contributes to the anti-malignant effects of the fusion of MSCs with cancer cells by regulating the expression of p21." (PMID 28404937, 2017). "FoxF1 also promotes mesenchymal cell migration by transcriptionally regulating integrin β3 and plays an important role in tumor stromal cells by stimulating cancer cell migration." (PMID 26908052, 2016). "This was the first demonstration of a role of FoxF1 in cancer." (PMID 26908052, 2016). "Recent studies reported deregulation of FOXF1 gene in human cancers." (PMID 26625197, 2016). "Therefore, it is possible that FOXF1-regulated chromatin remodeling can lead to either stimulation or inhibition of angiogenesis depending on other transcription factors that differentially expressed in normal and cancer lung tissues." (PMID 38589650, 2024). "FOXF1 is related to the positive regulation of cell migration, transcription, and the negative regulation of inflammatory response, suggesting its importance as a tumor suppressor gene regulating the inflammation, invasion, and metastasis of cancer stem cells (CSC)." (PMID 36661515, 2023). "Among these DEirlncRNAs included in the model, some have been revealed to be related to the development of cancers, such as LINC00958, FOXF1 adjacent non-coding developmental regulatory RNA (FENDRR), LINC01116, and LINC00941." (PMID 34408216, 2021). "We are still far to understand the roles of FOXF1 and FENDRR in the cancer development but there are suggestive functional data that can explain the tumor-suppressor features we have observed." (PMID 32284793, 2020). "On the contrary, FOXF1 has also been found to induce EMT and angiogenesis by activating SNAI1 and VEGFA, respectively, to promote cancer metastasis and angiogenesis in colon cancer." (PMID 32372224, 2020). "Using TANRIC, an interactive resource for the exploration of lncRNAs in large patient cohorts within 20 TCGA cancer types, we see that FENDRR expression is positively correlated to FOXF1 in 16 of 20 cancer types (P < 3.71 × 10−9)." (PMID 29757368, 2018).
cancer (continued). "In lung cancer, CAFs promote the proliferation and invasiveness of cancer cells by high expression of Forkhead box F1 and CXCL12.CAFs from squamous cell carcinoma of the head, neck and esophagus secrete hepatocyte growth factor to promote cancer invasion." (PMID 26954362, 2016). "To date, however, there is no unanimous consensus regarding the precise role of FOXF1 in cancer development." (PMID 40869921, 2025). "Additionally, we also identified several genes, including FOXS1, FOXP3, and FOXD2, showed elevated expression in a variety of tumors, while FOXF1, FOXP2, and FOXO1 were downregulated in the majority of cancers." (PMID 37401400, 2023). "Importantly, several and independent cancer datasets showed a significant positive correlation between FENDRR expression and FOXF1 RNA expression." (PMID 32284793, 2020). "This study shows that cancer-imposed changes in DNA hypermethylation may lead to reduced expression of FENDRR and FOXF1 in gastric CAMs." (PMID 30624614, 2019).
tumor (44 papers, 2012 to 2026). "In this study, we show that FOXF1 is expressed in normal lung EC but is decreased in the tumor-associated vasculature of human and mouse NSCLC." (PMID 38589650, 2024). "FOXF1 regulates pericyte coverage and perfusion of tumor-associated blood vessels, supporting the use of FOXF1-activating therapies for vascular normalization in NSCLC patients." (PMID 38589650, 2024). "Altogether, deletion of Foxf1 in endothelial cells caused structural abnormalities in tumor-associated blood vessels, associated with decreased vascular perfusion and increased hypoxia in tumor tissue." (PMID 38589650, 2024). "Based on endothelial cell sub-clustering, decreased Foxf1 mRNA was detected in tumor-associated capillary, arterial and venous ECs (Fig. EV1D)." (PMID 38589650, 2024). "Since defects in the FA DNA repair pathway are associated with hypersensitivity of tumor cells to DNA crosslinking agents, we examined functional consequences of FoxF1 depletion on cell survival after DNA damage." (PMID 26625197, 2016). "Previous studies with FoxF1-deficient mice have shown that FoxF1 is an important transcriptional regulator of embryonic development, however, its role in DNA repair of tumor cells remains uncharacterized." (PMID 26625197, 2016). "FoxF1 knockdown caused chromosomal instability, nuclear abnormalities, and increased tumor cell death in response to DNA-damaging agents." (PMID 26625197, 2016). "In response to DNA damage, FoxF1-deficient tumor cells showed significantly reduced FANCD2 monoubiquitination and FANCM phosphorylation, resulting in impaired formation of DNA repair foci." (PMID 26625197, 2016). "Similar to FA-deficient cells, increased number of chromosomal aberrations was observed in MMC-treated tumor cells deficient for FoxF1." (PMID 26625197, 2016). "We next examined tumor-associated angiogenesis in FOXF1-deficient mice." (PMID 38589650, 2024). "Interestingly, we have observed elevated endothelial cell numbers in FoxF1-deficient tumors, suggesting an increased tumor angiogenesis." (PMID 38589650, 2024). "Using transgenic mice in which Foxf1 was deleted or overexpressed in endothelial cells, we found that FOXF1 inhibits lung tumor growth and metastasis and normalizes tumor-associated blood vessels by maintaining Wnt/β-catenin signaling in ECs through transcriptional activation of FZD4." (PMID 38589650, 2024). "In summary, FOXF1 is decreased in tumor-associated endothelial cells in human and mouse NSCLC." (PMID 38589650, 2024). "In addition, HF-FoxF1 overexpression improved stability of FA core complex and its associated sub-complexes in FoxF1-depleted tumor cells." (PMID 26625197, 2016). "Depletion of FoxF1 inhibited DNA repair and caused chromosomal aberrations in tumor cells." (PMID 26625197, 2016). "CRISPR/Cas9-mediated inactivation of FOXF1 or its enhancers impaired tumor growth, even in the presence of PAX3-FOXO1." (PMID 40508013, 2025). "This process is driven by transcription factors like E2F1 and FOXF1 which promote rapid tumor growth by activating cell cycle and apoptotic pathways that contribute to neovascularization." (PMID 41450739, 2025). "Our data suggests that FOXF1 expression in endothelial cells is required for vascular normalization and that increasing FOXF1 in TECs can potentially improve anti-tumor inflammatory responses and drug deliveries." (PMID 38589650, 2024). "This study supports the concept that increasing expression of FOXF1 or its downstream target FZD4 in tumor endothelial cells, either pharmacologically or via gene therapy, can be considered for NSCLC treatment." (PMID 38589650, 2024). "Altogether, increased expression of FOXF1 in endothelial cells stimulates canonical WNT/β-catenin signaling, stabilizing tumor-associated blood vessels, and decreasing lung tumor growth and metastasis." (PMID 38589650, 2024).
tumor (continued). "Our findings that FOXF1 regulates its own expression through a transcriptional auto–regulatory loop are consistent with published studies demonstrating that FOXF1 functions as a “pioneer” transcription factor in gastrointestinal and myogenic tumor cells." (PMID 35440116, 2022). "In lung cancer, H3K4Ac marks have been detected in the transcription regulators FOXF1, and Bmi1 that promote tumor progression and stemness." (PMID 33803458, 2021). "The methylation status of the promoter CpG islands of FENDRR and FOXF1 was significantly different in tumor versus normal tissue." (PMID 32284793, 2020). "Other factors including FOXF1 and Bmi1 are also transcription regulators that promote tumor progression and tumor stemness." (PMID 32114978, 2020). "Approximately 84% and 96% of CpG islands were differentially methylated for FENDRR and FOXF1 respectively although mean methylation level difference between tumor and normal was even sensibly higher in the FOXF1 case." (PMID 32284793, 2020). "Here, we provide the first evidence suggesting that FOXF1 is a potential tumor suppressor, regulating senescence in human cells." (PMID 30119690, 2018). "Inactivation of FoxF1 leads to increased genomic instability and reduced survival of DNA-damaged tumor cells." (PMID 26625197, 2016). "FoxF1 physically binds to the FA core and I/D2 complexes, induces their binding to chromatin, promotes DNA repair and protects tumor cells from cell death in response to DNA-damaging agents." (PMID 26625197, 2016). "Forkhead box F1 (Foxf1) transcription factor is an important regulator of embryonic development but its role in tumor cells remains incompletely understood." (PMID 26625197, 2016). "Compared to control siRNA, FoxF1-depleted tumor cells showed a dose-dependent reduction in survival in response to MMC." (PMID 26625197, 2016). "FoxF1 is normally expressed in mesenchymal cells, which is difficult to reconcile with a tumor suppressing function of FoxF1 in epithelial cells." (PMID 26908052, 2016). "Cisplatin treatment increased FoxF1 protein levels as shown by Western blot of tumor lysate (lanes 1 and 2)." (PMID 26625197, 2016). "FoxF1 co-localized with FANCD2 in nuclear foci of DNA-damaged tumor cells in vitro and in vivo, suggesting that FoxF1 plays a role in DNA repair via interaction with FA complex proteins." (PMID 26625197, 2016). "In apparent contradiction to these results, there are reports of FoxF1 acting as a tumor suppressor." (PMID 26908052, 2016). "Using multiple human and mouse tumor cell lines and Foxf1+/− mice we demonstrated that FoxF1 physically binds to and increases stability of FA proteins." (PMID 26625197, 2016). "HeLa tumor cells stably expressing HF-FoxF1 were treated with Camptothecin to induce DNA damage response and the binding of FoxF1 with FA proteins was examined by IP." (PMID 26625197, 2016). "FANCD2, a marker of DNA repair foci co-localized with FoxF1 in nuclei of tumor cells treated with hydroxyurea, which induces a DNA-damage response." (PMID 26625197, 2016). "Consistent with previous studies, we found that FOXF1-deficient endothelial cells form leaky tumor vasculature with abnormal basement membrane lacking ColIV, leading to hypoxia in the lung tumor." (PMID 38589650, 2024). "It was shown that the mRNA expression levels of LINC00022 and FOXF1 in tumor tissues were significantly increased by the injection of LINC00022 overexpressing cells (4.9–7.8 fold vs Lv-NC group) and decreased by the injection of LINC00022 low-expressing cells (0.3–0.5 fold vs Lv-anti-NC group)." (PMID 35468741, 2022). "Immunohistochemistry also confirmed the expression of FOXF1 in tumor tissues." (PMID 35468741, 2022).